FAS (Fas cell surface death receptor)
Diseases named in the same sentence as FAS in open-access papers (continued):
Sharing a sentence is not in itself a finding about the gene and the disease.
infection (continued). "The mRNA levels of SREBP-1c, ACC1 and FAS were significantly increased in both the lean and DIO-infected mice after infection and peaked at 1 or 2 d.p.i (p<0.05) when compared with the uninfected mice." (PMID 30398974, 2018). "Previous studies reported that infection and inflammation increased the expression of SREBP-1c and its target genes, like FAS and ACC, while inhibited the expression of PPARα in vivo and in vitro." (PMID 30398974, 2018). "Considering the induction of apoptosis, the pbMEC of the high responder group also showed significantly stronger induction of the pro-apoptotic genes Bax, FAS, CASPASE 8, and CASPASE 3 post-infection, as compared to the low responder group." (PMID 29187202, 2017). "By day 52 (24 days after FIVC infection) the immunological response in dual infected cats is clearly distinct from all groups and is dominated by an elevated level of CD8, CD25, and FAS expressing cells, and increased numbers of lymphocytes and neutrophils." (PMID 19806226, 2009). "Single FIVC infections are characterized by higher IL12 and FAS levels and lymphocyte counts than dual infections." (PMID 19806226, 2009). "The balanced upregulation of pro-apoptotic (FAS, BBC3) and anti-apoptotic (BCL2A1, TRAF1) genes in TIGR4-infected cells likely mitigates extensive cell death, enabling Spn to maintain host cell viability for sustained infection." (PMID 40475528, 2025). "In the present study, 109 CFUs/mL E. coli could up-regulate the expression of hepatic SREBP-1c, ACC1 (one subset of ACC) and FAS, and down-regulate the expression of PPARα and CPT-1α, which was accordance with LPS-induced infection in CD-1 mice." (PMID 30398974, 2018). "At week 1 post infection CXCR4, FAS and PTPN22 showed higher expression in line L10H." (PMID 26819139, 2016). "In our analysis, we observe that a subset of these cytokines reported to be present in the serum also show transcriptional upregulations in PBMCs by 4 days post-infection (IL6, IL1B, IL1RN, CCL8, CXCL10) and by 7 days post-infection (CCL2, CCL3, CSF1, TNF, CXCL1, FAS and CXCL8)." (PMID 27595844, 2016). "This was in contrast with our previous observations that fibroblast cell lines do not undergo apoptosis upon ΔM36 infection, unless stimulated with anti-FAS antibodies." (PMID 23271968, 2012). "When we stained liver sections with FAS- and HCV-specific antibodies, we found that expression of FAS does not depend on the presence of HCV in the cells, but is a host reaction to infection of neighbouring cells." (PMID 19242562, 2009). "The expression analysis of the cells showed that all cells were able to stimulate the expression of both genes with the exception of GBM27, that was unable to induce FAS expression, and GBM128B that did not stimulate TRAIL expression upon infection." (PMID 32516884, 2020). "However, analysis of FAS polymorphisms in subgroups of patients with and without anti-GM1 antibodies suggests involvement of the FAS -670 AG genotype and FAS -1377/ -670 GG haplotype as stimulators of the cross-reactive immune response following antecedent infection in GBS." (PMID 29432441, 2018). "The addition of IFNγ after infection not only resulted in a dramatic increase of the translation of the before mentioned genes but also in the translation of IFNß1, IL12ß, MIP1 and CCL3, CCL4, NOS2 and SOD2, and FAS but, nevertheless, did not prevent multiplication of the bacteria." (PMID 32462327, 2020).
immune disorder (9 papers, 2014 to 2025). "FAS gene polymorphisms have been mainly studied in association with malignancies and immune system diseases." (PMID 38212800, 2024). "Fas cell surface death receptor (FAS) has been found to play a critical role in the physiological regulation of programmed cell death as a member of TNF-receptor superfamily and has been implicated in the pathogenesis of several malignancies and immune system diseases." (PMID 36186479, 2022).
metabolic disorders (8 papers, 2013 to 2025). "PPARγ participates in mediating metabolic disorder via numerous downstream adipogenic and lipogenic genes, which are important for adipocyte maturation, lipid accumulation, and insulin-sensitive glucose transport, including FAS, ACC, aP2, SCD-1, and CD36." (PMID 23533476, 2013). "These additional putative mono/oligogenic SLE genes are involved in type I IFN regulation (DDX58, NLRC4 and PACSIN1), disruption of B cell and T cell tolerance (DOCK8, FAS and LRBA) and metabolic disorders (CYBB, MAN2B1, SLC7A7)." (PMID 40386946, 2025). "The metabolic disorder in males that had been exposed to metformin in utero was confirmed by a dysregulation of CPT1 and FAS, markers of mitochondrial β-oxidation and fatty acid production, respectively." (PMID 34745014, 2021). "Measuring the activity or expression levels of signaling molecules (FAS, ATGL, LPL, PPARs, MMPs, α-SMA, and certain indicative proteins) and transcription factors can provide insights into their mechanisms of action in fibrosis, metabolic disorders, and chronic diseases." (PMID 37895842, 2023).
hematologic malignancies (4 papers, 2015 to 2025). "Conversely, its potential pro-oncogenic role in hematologic malignancies, via resistance to FAS-induced apoptosis, needs to be investigated at the clinical level." (PMID 33322542, 2020). "It is activated in a variety of tumors, including hematologic malignancies and solid tumors; however, the activation of NF-κB induces the expression of proapoptotic genes such as TRAIL, FAS (CD95), PUMA, DR4 and DR5 to promote apoptosis and reduce tumorigenesis." (PMID 38612387, 2024). "Furthermore, siQKI decreased FAS transcript levels in MEC2 but not BJAB cells, suggesting that different molecular mechanisms control FAS expression in these two types of hematological malignancies." (PMID 26337206, 2015).
neurodegenerative disease (4 papers, 2013 to 2024). A disorder of the central nervous system characterized by gradual and progressive loss of neural tissue and neurologic function. "Fas-FasL play a crucial role in elimination of inflammatory immune cells from the nervous system and are implicated in several neurodegenerative diseases, thus FAS-FASL genotypes may affect susceptibility and disease severity." (PMID 29432441, 2018).
bacterial infections (3 papers, 2016 to 2024). "Recently, it was demonstrated that neutrophils are killed by engagement of the death receptor FAS/CD95 during viral and bacterial infections." (PMID 29495595, 2018).
neurological diseases (3 papers, 2009 to 2025). "From this figure, we can easily conclude that aging genes FAS and APP are important to the linkage of immunological and neurological diseases." (PMID 19779549, 2009).
kidney disease (2 papers, 2021 to 2023). "Cases classified with ACR-7 (renal disorder/LN) were positively associated with FAS but negatively associated with hepatocyte growth factor (HGF)." (PMID 36858042, 2023). "This strain has a mutation of the FAS gene that disrupts normal Fas-mediated apoptosis and results in ineffective clearing of autoreactive lymphocytes, leading to nuclear autoantibody production, hypergammaglobulinemia, lymphadenopathy, skin, and kidney disease." (PMID 34868008, 2021).
FAS also shares sentences with these, for which no sentence is quoted: acute lymphoblastic leukemia (7 papers); influenza (7); cardiovascular disease (6); chronic lymphocytic leukemia (6); liver (6); acute T-cell leukemia (5); non-small cell lung carcinoma (5); dermatitis (4); Immunodeficiency (4); renal cell carcinoma (4); sarcoidosis (4); ZIKV infection (4); AIDS (3); Burkitt lymphoma (3); chronic myelogenous leukemia (3); genetic disorder (3); hematological cancer (3); insulinoma (3); liver cirrhosis (3); lung squamous cell carcinoma (3); malignant glioma (3); myelogenous leukemia (3); non-alcoholic steatohepatitis (3); non-Hodgkin lymphoma (3); parasitemia (3); acute kidney injury (2); adult T-cell leukemia (2); alcohol (2); anaplastic large cell lymphoma (2); autoimmune hemolytic anemia (2).
A further 144 diseases each share a sentence with FAS in 2 papers or fewer.